PNO1 (partner of NOB1 homolog)
Description:
Part of the small subunit (SSU) processome, first precursor of the small eukaryotic ribosomal subunit. During the assembly of the SSU processome in the nucleolus, many ribosome biogenesis factors, an RNA chaperone and ribosomal proteins associate with the nascent pre-rRNA and work in concert to generate RNA folding, modifications, rearrangements and cleavage as well as targeted degradation of pre-ribosomal RNA by the RNA exosome. Positively regulates dimethylation of two adjacent adenosines in the loop of a conserved hairpin near the 3'-end of 18S rRNA.
Synonyms: RRP20; KHRBP1
Tractability: Small molecule: a structure with a bound ligand is known. PROTAC: ubiquitination databases record sites on it; its protein half-life has been measured.
Gene: Protein-coding gene on chromosome 2 (68,157,888 to 68,176,238, forward strand). Ensembl gene ENSG00000115946.
Subcellular location: Nucleus, nucleolus
Subcellular location (Human Protein Atlas): Nucleoli; Nucleoplasm
Pathways (Reactome):
Metabolism of RNA: Major pathway of rRNA processing in the nucleolus and cytosol; rRNA modification in the nucleus and cytosol
Gene Ontology:
Molecular function: protein binding; RNA binding; nucleic acid binding
Biological process: ribosomal small subunit biogenesis; maturation of SSU-rRNA
Cellular component: nucleolus; small-subunit processome; cytosol; nucleoplasm; nucleus
Genetic constraint (gnomAD): Loss-of-function variants: 7 observed, 13.16 expected, observed/expected ratio (o/e) 0.53, 90% interval 0.3 to 1. The upper end of that interval is the gene's LOEUF score, 1, which puts it in group 4 of 6, group 1 being the genes least tolerant of losing a copy. Missense variants: 192 observed, 207.75 expected, observed/expected ratio (o/e) 0.92, 90% interval 0.82 to 1.04. Synonymous variants: 65 observed, 78.73 expected, observed/expected ratio (o/e) 0.83, 90% interval 0.68 to 1.01.
Homologues: Orthologues: chimpanzee PNO1 (99% identical), macaque PNO1 (99% identical), dog PNO1 (93% identical), guinea pig PNO1 (93% identical), pig PNO1 (93% identical), rat Pno1 (93% identical), mouse Pno1 (91% identical), tropical clawed frog pno1 (75% identical), zebrafish pno1 (70% identical), Drosophila melanogaster l(1)G0004 (56% identical), Caenorhabditis elegans pno-1 (53% identical).
Diseases named in the same sentence as PNO1 in open-access papers:
PNO1 is named in the same sentence as 27 diseases in open-access papers, as found by Europe PMC text mining. Sharing a sentence is not in itself a finding about the gene and the disease. The quoted sentences say what the papers report.
hepatocellular carcinoma (9 papers, 2021 to 2025). A malignant tumor that arises from hepatocytes. "PNO1 expression was significantly higher in both hepatocellular carcinoma and fibrolamellar carcinoma compared to that in normal tissues." (PMID 38722284, 2024). "We next examined the PNO1 expression at different histological subtype (hepatocellular carcinoma and fibrolamellar carcinoma)." (PMID 38722284, 2024). "In hepatocellular carcinoma, celecoxib inhibited PNO1 expression and tumour growth through modulation of AKT/mTOR signalling pathway." (PMID 36625087, 2023). "PNO1 regulates apoptosis and autophagy of hepatocellular carcinoma through MAPK signaling pathway, facilitating the cancer progression." (PMID 36751636, 2023). "In hepatocellular carcinoma, PNO1 inhibition blocked SLC7A11 expression and the xCT activity followed cystine intake, which downregulated the accumulation of GSH and expression of GPX4 and induced ferroptosis." (PMID 37268653, 2023). "For instance, PNO1 enhances GSH biosynthesis by promoting autophagy, consequently diminishing the susceptibility of hepatocellular carcinoma (HCC) cells to ferroptosis." (PMID 39548421, 2024).
lung adenocarcinoma (7 papers, 2020 to 2024). A carcinoma that arises from the lung and is characterized by the presence of malignant glandular epithelial cells. "Overall, our data suggest that PNO1 can be used as a diagnostic biomarker, and also can be an attractive therapeutic target for the treatment of lung adenocarcinoma." (PMID 36625087, 2023). "In our present study, we aimed to explore the functional roles and the underlying molecular mechanisms of PNO1 in human lung adenocarcinoma (LUAD)." (PMID 32483111, 2020). "In lung adenocarcinoma, higher expression of PNO1 has been associated with poor survival." (PMID 36625087, 2023). "Negatively regulated PNO1 expression by miR‐340‐5p promotes lung adenocarcinoma progression through Notch signalling pathway." (PMID 38722284, 2024). "In conclusion, PNO1 can be used as a diagnostic biomarker for lung adenocarcinoma, and inhibition of PNO1 by CRISPR/Cas9 technology can be a useful strategy for the treatment of lung adenocarcinoma." (PMID 36625087, 2023). "Our data suggest that the inhibition of PNO1 can inhibit lung adenocarcinoma by suppressing the production of inflammatory cytokines and chemokines." (PMID 36625087, 2023). "The over-expression of PNO1 was found in lung adenocarcinoma through the analysis based on bioinformatics databases and clinical investigation." (PMID 38071381, 2023). "PNO1 expression was significantly higher in all stages (stages 1–4) of lung adenocarcinoma development compared to normal tissues." (PMID 36625087, 2023). "In the present study, inhibition of PNO1 expression by the CRISPR/Cas9 technique suppressed lung adenocarcinoma." (PMID 36625087, 2023). "In the present study, PNO1 was overexpressed in lung adenocarcinoma, and its inhibition by CRISPR/Cas9 technology inhibited cell proliferation, motility, migration, and invasion, and induced apoptosis." (PMID 36625087, 2023). "According to TCGA data, PNO1 expression in lung adenocarcinoma patients increased with stage of development, nodal metastasis, and smoking." (PMID 36625087, 2023). "PNO1 expression was significantly higher in both male and female lung adenocarcinoma patients than those in normal lung tissues." (PMID 36625087, 2023). "Further studies are needed to examine the clinical potential of PNO1 inhibition in lung adenocarcinoma." (PMID 36625087, 2023). "The expression of PNO1 was significantly higher in lung adenocarcinoma compared to normal lung tissues." (PMID 36625087, 2023). "PNO1 expression in lung adenocarcinoma patients increased with stage, nodal metastasis, and smoking." (PMID 36625087, 2023). "Since dysregulated signalling through the Notch receptors promotes lung adenocarcinoma, we measured the effects of PNO1 inhibition on the Notch pathway." (PMID 36625087, 2023). "Our findings suggest that PNO1 knockdown can be a beneficial therapeutic agent for the treatment of lung adenocarcinoma." (PMID 36625087, 2023). "Lung adenocarcinoma tissues from males expressed higher PNO1 than those from females, suggesting the influence of sex on PNO1 expression." (PMID 36625087, 2023). "Our previous study has shown that PNO1 is associated with the progression of various cancers, including HCC and lung adenocarcinoma." (PMID 36446769, 2022). "Our previous study has shown that PNO1 is highly expressed in lung adenocarcinoma tissues and is closely related to poor prognosis." (PMID 34050137, 2021). "Similarly, another study has demonstrated the oncogenic role of PNO1 where PNO1 promoted lung adenocarcinoma progression through the Notch signalling pathway." (PMID 36625087, 2023). "We next compared the expression of PNO1 among smokers with lung adenocarcinoma." (PMID 36625087, 2023). "We next measured the expression of PNO1 in both male and female lung adenocarcinoma patients." (PMID 36625087, 2023).
lung adenocarcinoma (continued). "PNO1 expression was higher in lung adenocarcinoma tissues compared to normal tissues." (PMID 36625087, 2023). "Therefore, PNO1 inhibition by genetic or pharmacological means offers new hope for the treatment of lung adenocarcinoma." (PMID 36625087, 2023). "In addition to inhibiting the growth of lung adenocarcinoma, PNO1 knockdown also inhibited Notch signalling pathway, and cytokines and chemokines." (PMID 36625087, 2023). "Lung adenocarcinoma tissues from males expressed higher PNO1 than those from females." (PMID 36625087, 2023). "The purpose of this study was to examine whether PNO1 can be used as a biomarker for lung adenocarcinoma and also examine the molecular mechanisms by which PNO1 knockdown by CRISPR/Cas9 inhibited growth and epithelial–mesenchymal transition (EMT)." (PMID 36625087, 2023). "Therefore, understanding the expression and biological function of PNO1 is crucial for effectively managing lung adenocarcinoma." (PMID 36625087, 2023). "However, lung adenocarcinoma from male patients showed significantly higher PNO1 expression than those from female patients." (PMID 36625087, 2023). "We next examined whether the expression of PNO1 changed during various stages of lung adenocarcinoma." (PMID 36625087, 2023). "For instance, lung cancer cell proliferation and EMT were suppressed by PNO1 (RNA-binding protein)/CRISPR/Cas9 through inhibiting the Notch signalling pathway in lung adenocarcinoma." (PMID 37569598, 2023). "The expression of PNO1 was significantly higher in lung adenocarcinoma than in normal lung tissues." (PMID 36625087, 2023).
colorectal cancer (6 papers, 2020 to 2025). A primary or metastatic malignant neoplasm that affects the colon or rectum. "Early B cell factor 1 (EBF1) has been identified as an upstream transcription factor of the potential oncogene PNO1 and is involved in the growth of colorectal cancer (CRC) cells." (PMID 32676457, 2020). "In addition to the function of PNO1 in ribosome biogenesis, recent studies have reported that PNO1 may affect the progression of colorectal cancer (CRC) and urinary bladder carcinoma." (PMID 34050137, 2021).
liver cancer (4 papers, 2021 to 2024). An epithelial or non-epithelial malignant neoplasm that arises from the liver. "The combination of PNO1 inhibition with drugs causing ferroptosis induction, particularly sorafenib, the first-line drug associated with ferroptosis in liver cancer shows therapeutic promise in vitro and in vivo." (PMID 36446769, 2022). "PNO1 knockout inhibited liver cancer cell viability, colony formation and EMT and induced apoptosis." (PMID 38722284, 2024). "Out provides a potential therapeutic strategy for liver cancer that combines PNO1 targeting and ferroptosis activators." (PMID 36446769, 2022). "In addition to inhibiting the growth of liver cancer cells, PNO1 knockout also inhibited Notch signalling pathway, which has been shown to regulate cancer initiation, progression and metastasis." (PMID 38722284, 2024). "GO analysis suggested that PNO1 affected the proliferation and apoptosis of liver cancer cells." (PMID 34050137, 2021). "NUDCD1, ENY2, PNO1, CCT4 and PSMD14 are considered to promote the proliferation, invasion and treatment resistance of tumor cells in a variety of cancers, including pancreatic cancer, rectal cancer, liver cancer, breast cancer, glial cancer and head and neck squamous cell carcinoma." (PMID 37827692, 2023).
breast carcinoma (3 papers, 2020 to 2023). "PNO1 may be used as a promising biomarker in breast cancer (unpublished data)." (PMID 32483111, 2020). "Furthermore, we also demonstrated the functional role of PNO1 in breast cancer." (PMID 32483111, 2020). "Thus, we hypothesize that PNO1 may act as a potential prognostic marker in adenocarcinoma-like malignancies according to the findings for LUAD, breast cancer and CRC." (PMID 32483111, 2020).
lung carcinoma (3 papers, 2022 to 2023). "Since PNO1 expression has been associated with lung cancer progression and poor survival, we examined the effects of PNO1 inhibition on lung cancer growth." (PMID 36625087, 2023). "The main objective of this paper is to assess whether PNO1 can be used as a diagnostic marker for lung cancer and examine the molecular mechanisms by which PNO1 inhibition regulates lung cancer growth and epithelial–mesenchymal transition (EMT) in lung cancer." (PMID 36625087, 2023). "In conclusion, our study has demonstrated that inhibition of PNO1 expression can inhibit lung cancer growth and EMT by suppressing the NOTCH pathway." (PMID 36625087, 2023). "Smokers with lung cancer and reformed smokers (>15 years) showed significantly higher expression of PNO1 than non‐smokers and reformed smokers (<15 years)." (PMID 36625087, 2023). "The expression of PNO1 was significantly higher in lung cancer cells than in adjacent normal tissue, suggesting it can be used as a diagnostic marker for lung cancer." (PMID 36625087, 2023). "PNO1 knockdown inhibited lung cancer cell viability, colony formation, and EMT, and induced apoptosis." (PMID 36625087, 2023). "We next sought to examine the effects of inhibiting PNO1 on lung cancer (A549 and H460) cell proliferation." (PMID 36625087, 2023). "Since PNO1/CRISPR/Cas9 inhibited cell proliferation in both A549 and H460 cells, we next sought to examine the effects of inhibiting PNO1 expression on lung cancer cell apoptosis." (PMID 36625087, 2023). "Downregulation of the Notch signalling pathway sensitizes lung cancer cells to cisplatin, potentially representing a pathway through which PNO1 expression promotes resistance to platinum-based chemotherapy." (PMID 35681748, 2022). "PNO1/CRISPR/Cas9 inhibited the mRNA and protein expression of Snail, Slug, and Zeb1 in lung cancer A549 and H460 cells." (PMID 36625087, 2023). "Since PNO1/CRISPR/Cas9 inhibited the expression of PNO1, we next sought to examine the effects of inhibiting PNO1 on colony formation by lung cancer cells." (PMID 36625087, 2023). "Since PNO1 knockdown inhibited the expression of PTGS2, a gene involved in inflammation, we sought to examine the effects of inhibiting PNO1 on the expression of inflammatory cytokines (IL‐1α and IL‐8) in lung cancer cells." (PMID 36625087, 2023). "PNO1/CRISPR/Cas9 inhibited growth and EMT of lung cancer cells by suppressing the Notch pathway." (PMID 36625087, 2023). "Similarly, PNO1/CRISPR/Cas9 inhibited the expression of Notch target genes Hes1 and Hey1 in lung cancer A549 and H460 cells." (PMID 36625087, 2023). "In the present study, inhibition of PNO1‐induced p21 and suppressed CCND1 in lung cancer cells." (PMID 36625087, 2023). "PNO1/CRISPR/Cas9 inhibited the expression of Notch1, Notch2, Notch3 Jagged1, and DLL1 in lung cancer A549 and H460 cells." (PMID 36625087, 2023).
bladder cancer (2 papers, 2020 to 2021). "The resulting ΔCt of 7.96 ± 0.181 for T24 and 7.59 ± 0.044 for 5637 suggested high expression of PNO1 in both bladder cancer cell lines." (PMID 31800162, 2020). "We studied the role of PNO1 in two bladder cancer cell lines, T24 and 5637." (PMID 31800162, 2020). "For example, PNO1, a novel RBP isolated from the human kidney, functions as an oncogene in urinary bladder cancer by promoting proliferation and inhibiting apoptosis of urinary bladder cancer cells." (PMID 33685397, 2021).
lymph node metastasis (2 papers, 2020 to 2024). "PNO1 expression was positively associated with tumour stage, lymph node metastasis and poor survival." (PMID 38722284, 2024). "We also found that PNO1 mRNA expression was positively correlated with lymph node metastasis." (PMID 32483111, 2020).
pancreatic cancer (2 papers, 2023 to 2024). "Previous results have shown that silencing PNO1 in pancreatic cancer shows a series of characteristics of ferroptosis activation." (PMID 39769097, 2024). "Mechanistically, E2F Transcription Factor 1 (E2F1) may bind to the promoter of PNO1 to promote the transcriptional expression of PNO1, thus inhibiting ferroptosis and promoting the malignant progression of pancreatic cancer." (PMID 39769097, 2024). "However, whether the process of pancreatic cancer promoted by PNO1 is ferroptosis-dependent remains to be discussed." (PMID 39769097, 2024).
bladder urothelial carcinomas (1 paper, 2020). "We first evaluated PNO1 expression in 56 bladder urothelial carcinomas by immunohistochemistry (IHC)." (PMID 31800162, 2020).
colon cancer (1 paper, 2022).
esophageal cancer (1 paper, 2023). A primary or metastatic malignant neoplasm involving the esophagus. "The deletion of PNO1 significantly reduced the viability and motility of esophageal cancer cells, and PNO1 might played promoting roles in this cancer progression through mediating AKT1, Twist, Myc, mTOR, MMP2, NF-κB p65 and CTNNB1 expression." (PMID 38071381, 2023).
fibrolamellar carcinoma (1 paper, 2024). "PNO1 expression was significantly higher in HCC compared to that in fibrolamellar carcinoma or normal tissues." (PMID 38722284, 2024). "The maximum expression of PNO1 was observed in fibrolamellar carcinoma." (PMID 38722284, 2024).